SOX17 (SRY-box transcription factor 17)
Description:
Acts as a transcription regulator that binds target promoter DNA. Binds to the sequences 5'-AACAAT-'3 or 5'-AACAAAG-3'. Modulates transcriptional regulation via WNT3A. Inhibits Wnt signaling. Promotes degradation of activated CTNNB1. Plays a key role in the regulation of embryonic development. Required for normal development of the definitive gut endoderm. Required for normal looping of the embryonic heart tube. Plays an important role in embryonic and postnatal vascular development, including development of arteries. Plays an important role in postnatal angiogenesis, where it is functionally redundant with SOX18. Required for the generation and maintenance of fetal hematopoietic stem cells, and for fetal hematopoiesis. Probable transcriptional activator in the premeiotic germ cells.
Synonyms: PPH7; VUR3
Tractability: No criterion of Open Targets' tractability assessment is met for any kind of drug.
Target class: Transcription factor
Gene: Protein-coding gene on chromosome 8 (54,457,935 to 54,460,892, forward strand). Ensembl gene ENSG00000164736.
Subcellular location: Nucleus
Subcellular location (Human Protein Atlas): Nucleoplasm; Nuclear membrane
Pathways (Reactome):
Developmental Biology: Developmental Lineage of Multipotent Pancreatic Progenitor Cells; Formation of definitive endoderm
Reproduction: Specification of primordial germ cells
Signal Transduction: Deactivation of the beta-catenin transactivating complex
Gene Ontology:
Molecular function: beta-catenin binding; protein binding; RNA polymerase II-specific DNA-binding transcription factor binding; DNA-binding transcription activator activity, RNA polymerase II-specific; DNA-binding transcription factor activity, RNA polymerase II-specific; RNA polymerase II cis-regulatory region sequence-specific DNA binding; transcription cis-regulatory region binding; DNA binding; DNA-binding transcription factor activity; sequence-specific DNA binding; sequence-specific double-stranded DNA binding
Biological process: cardiac cell fate determination; endoderm formation; metanephros development; negative regulation of canonical Wnt signaling pathway; negative regulation of cell growth; positive regulation of transcription by RNA polymerase II; protein destabilization; protein stabilization; ureter development; angiogenesis; cardiogenic plate morphogenesis; embryonic foregut morphogenesis; embryonic heart tube development; embryonic heart tube morphogenesis; endocardial cell differentiation; endocardium formation; endodermal cell fate specification; endodermal digestive tract morphogenesis; heart development; heart formation; heart looping; outflow tract morphogenesis; positive regulation of DNA-templated transcription; regulation of cardiac cell fate specification; regulation of DNA-templated transcription; and 9 more
Cellular component: nucleus; transcription regulator complex; chromatin; nucleoplasm
Genetic constraint (gnomAD): Loss-of-function variants: 4 observed, 14.9 expected, observed/expected ratio (o/e) 0.27, 90% interval 0.13 to 0.61. The synonymous counts are far from expectation, so gnomAD's model fits this gene poorly and the ratio says little. Missense variants: 633 observed, 535.56 expected, observed/expected ratio (o/e) 1.18, 90% interval 1.11 to 1.26. Synonymous variants: 357 observed, 261.64 expected, observed/expected ratio (o/e) 1.36, 90% interval 1.25 to 1.49.
Gene-disease validity (ClinGen):
ClinGen rates the evidence that SOX17 causes each of these diseases.
pulmonary arterial hypertension (autosomal dominant): Definitive. Pulmonary arterial hypertension (PAH) is a group of diseases characterized by mean pulmonary artery pressure >20 mmHg and elevated pulmonary arterial resistance leading to right heart failure.
Homologues: Orthologues: chimpanzee SOX17 (99% identical), macaque SOX17 (97% identical), pig SOX17 (90% identical), dog SOX17 (89% identical), mouse Sox17 (85% identical), rat Sox17 (84% identical), guinea pig SOX17 (83% identical), tropical clawed frog sox17b (52% identical), zebrafish sox17 (41% identical), Drosophila melanogaster Sox14 (21% identical), Drosophila melanogaster Sox21a (17% identical). Paralogues in human: SOX7 (39% identical), SOX18 (38% identical), SOX9 (24% identical), SOX8 (21% identical), CFAP65 (21% identical), SOX1 (21% identical), SOX10 (21% identical), SOX4 (20% identical), SOX3 (20% identical), SOX30 (20% identical), SOX11 (19% identical), SOX12 (19% identical), and 8 more.
Diseases named in the same sentence as SOX17 in open-access papers:
SOX17 is named in the same sentence as 153 diseases in open-access papers, as found by Europe PMC text mining. Sharing a sentence is not in itself a finding about the gene and the disease. The quoted sentences say what the papers report.
lung carcinoma (32 papers, 2012 to 2025). "We have demonstrated that aPC-EVs via miR-200a transfer elicit pro-tumorigenic effects by downregulating SOX17 expression and low SOX17 level is associated with poor survival of lung cancer patients." (PMID 41271627, 2025). "For lung cancer risk prediction, univariate logistic regression analysis revealed that methylation levels of SOX17, HOXA9, CDO1, and TAC1 were significantly related to lung cancer risk." (PMID 36153611, 2022). "SOX17 downregulation is also observed in human lung cancer tissues associated with poor survival." (PMID 41271627, 2025). "miR-200a upregulation and SOX17 downregulation are consistently observed in lung cancer tissues in the UALCAN portal database of clinical specimens." (PMID 41271627, 2025). "More than a decade ago, SOX17 was found to be expressed in endothelial cells of tumor‐penetrating vessels in murine‐implanted lung carcinoma." (PMID 39385307, 2024). "Collectively, this study reveals that the methylation of 7 genes (TAC1, CDO1, HOXA9, ZFP42, SOX17, RASSF1A and SHOX2) has a big significance in the diagnosis of lung cancer and achieved a diagnostic model with high sensitivity and specificity." (PMID 38315228, 2024). "In this current study, we found that HOXA7 DNA methylation was correlated with higher NDI, and methylation of HOXA7, SOX17, ZFP42, HOXA9, CDO1 and TAC1was associated with advanced stage disease in lung cancer." (PMID 39107707, 2024). "The KM plot analysis showed that the overregulation of three oncogenes (SOX4, BZW2, and FOXM1) as well the downregulation of four tumor suppressors (SOX17, ZBTB16, TAL1, and KLF4) is associated with worse overall survival (OS) for lung cancer patients." (PMID 36661515, 2023). "SOX17 transcript has also been proven to play a crucial role in the progression of various cancers, including lung cancer, hepatic carcinoma, and gastric cancer." (PMID 34409028, 2021). "A colony-formation assay shows that SOX17 suppresses lung cancer cell proliferation and inhibits the Wnt-signaling pathway." (PMID 33152990, 2020). "Dysregulation of SOX17 is a major key component in the development and progression of numerous types of cancer, including breast and endometria cancer, lung cancer, esophageal and gastric cancer." (PMID 33152990, 2020). "The role of SOX17 proteins in the molecular biology of lung cancer has only been partially investigated." (PMID 33152990, 2020). "As elevated odds ratios ranged from 2.81 to 7.19, logistic regressions analyses also indicated that the methylation of CDO1, TAC1, SOX17, and HOXA7 were closely related to increasing lung cancer risk." (PMID 32138766, 2020). "The data suggested that SOX17 expression was significantly downregulated in only lung cancer." (PMID 41271627, 2025). "In lung cancer, STK11 loss causes a metastasis-like subpopulation of cancer cells in primary tumors and metastases to activate the early endodermal transcription factor, Sox17." (PMID 38461159, 2024). "The downregulation of SOX17 might also be related to the promoter methylation of CpG sites, suggesting that demethylating drugs would be a promising approach for lung cancer treatment." (PMID 36661515, 2023). "Promoter methylation of SOX17 also showed promise as a lung cancer biomarker." (PMID 37742993, 2023). "SOX17 methylation status has also proved to be correlated with lung cancer differentiation." (PMID 33152990, 2020). "Additionally, the epigenetic mechanisms of the SOX17 control have been identified in lung cancer cell lines and primary human lung cancer tissues." (PMID 33152990, 2020). "Therefore, SOX17 methylation status may serve as a potential marker for lung cancer detection and may suggest that females are more vulnerable to SOX17-related lung carcinogenesis." (PMID 33152990, 2020).
lung carcinoma (continued). "Methylation analysis in the plasma DNA of certain genes (SOX17, TAC1, HOXA7, SOX17, HOXA9 ZFP42h) using quantitative methylation-specific real-time PCR and methylation-on-beads for cancer-specific genes showed a strong association with the diagnosis of early-stage lung carcinoma." (PMID 30917582, 2019). "Several markers (FOXA1 and RASSF1A) were methylated in both lung cancer and PCa, while SEPT9 and SOX17 were hypermethylated across lung, colorectal, and prostate cancers." (PMID 41008642, 2025). "Here, we explored the significance of the DNA methylation of 7 genes including TAC1, CDO1, HOXA9, ZFP42, SOX17, RASSF1A and SHOX2 in the blood cfDNA samples in distinguishing lung cancer from benign nodules and healthy individuals." (PMID 38315228, 2024). "However, the expression profile of SOX17 is largely unknown in human lung cancer." (PMID 39385307, 2024). "In this study, we explored the significance of the DNA methylation of 7 genes including TAC1, CDO1, HOXA9, ZFP42, SOX17, RASSF1A and SHOX2 in the blood cfDNA samples in distinguishing lung cancer from benign nodules and healthy individuals." (PMID 38315228, 2024). "Here, we compared the DNA methylation status of 7 genes including TAC1, CDO1, HOXA9, ZFP42, SOX17, RASSF1A and SHOX2 in lung cancer cases with I–IV stages." (PMID 38315228, 2024). "Then, we explored the diagnosis value of the DNA methylation status of 7 genes including TAC1, CDO1, HOXA9, ZFP42, SOX17, RASSF1A and SHOX2 in lung cancer." (PMID 38315228, 2024). "To this end, we compared the DNA methylation status of 7 genes including TAC1, CDO1, HOXA9, ZFP42, SOX17, RASSF1A and SHOX2 in lung cancer cases with different stages." (PMID 38315228, 2024). "Studies have shown that SOX17, RASSF1A, and SHOX2 methylation can be applied as markers for lung cancer screening and detection." (PMID 39766341, 2024). "Twelve of 20 genes (60%) in the list were methylation driver genes described previously in lung cancer, such as CDO1, SLIT2, SOX17 and TCF21." (PMID 33859751, 2021). "Promoter methylation of eight lung cancer-specific genes (CDO1, TAC1, SOX17, HOXA7, HOXA9, GATA4, GATA5, and PAX5) was detected using nanoparticle-based DNA extraction (MOB) followed by qMSP." (PMID 32138766, 2020). "The SOX17 promoter is hypermethylated in cholangiocarcinoma (CCA) tissues, lung cancer, gastric cancer, liver cancer, and breast cancer." (PMID 31405379, 2019). "An epigenetic classifier including four genes (HOXA9, RASSF1A, SOX17, and TAC1) that was evaluated in sputum by ddPCR reached an AUROC of 0.92 for lung cancer detection." (PMID 31817025, 2019). "For example, P16, HOXA11 (Homeobox A11) and SOX17 (SRY-box 17) showed abnormal hypermethylation at their promoters, they were considered as biomarkers for lung cancer detection and prognosis prediction." (PMID 29169318, 2017). "In conclusion, despite these limitations, our meta-analysis advocates that methylated SOX17, CDO1, ZFP42, TAC1, FAM19A4, FHIT, MGMT, p16, and RASSF1A are useful biomarkers in the screening and auxiliary detection of lung cancer." (PMID 28644424, 2017). "One of the previously reported methylated genes was SOX17, a canonical WNT antagonist previously shown functionally hypermethylated in breast, colorectal and lung cancers." (PMID 29169318, 2017). "Of 30 top ranked genes, FAM107A, MAMDC2, SOX17, TCF21, PTPRH, and CDO1 have been previously reported with aberrant DNA methylation in lung cancer." (PMID 27610367, 2016). "Breast and lung cancer have many common prognostic signatures, such as hypermethylation of BRCA1, SOX17, and TLX3." (PMID 24842468, 2014). "While many biomarkers have been shown to be viable for gastric and urinary cancers such as bladder and CRC, one study also reported a successful DNA methylation analysis (1.7) of a panel (CDO1, TAC1, HOXA7, HOXA9, SOX17, and ZFP42 promoters) to diagnose lung cancer." (PMID 40141826, 2025).
lung carcinoma (continued). "Moreover, we compared the DNA methylation status of 7 genes (TAC1, CDO1, HOXA9, ZFP42, SOX17, RASSF1A and SHOX2) in lung cancer cases from the mass and GGNs groups." (PMID 38315228, 2024). "Following a large literature review, we explored the performance of the DNA methylation of 7 genes including TAC1, CDO1, HOXA9, ZFP42, SOX17, RASSF1A and SHOX2 in the blood cfDNA samples in distinguishing lung cancer from benign nodules and healthy individuals." (PMID 38315228, 2024). "According to the TRN of lung cancer, SOX4, FOXM1, ETV4, HOXC6, and E2F3 are the main positive regulators, whereas SOX17, KLF4, and ZBTB16 are the main negative regulators of transcription, controlling the expression of other TFs and target genes in lung cancer." (PMID 39228892, 2024). "Therefore, SOX17 must be downregulated and SOX4 upregulated to allow for the establishment and progression of lung cancer." (PMID 36661515, 2023). "The seven top deregulated transcription factors (SOX4, SOX17, BZW2, FOXM1, ZBTB16, TAL1, and KLF4) consistently appear to be co-expressed with other frequent DEGs and transcription factors throughout the analysis in lung cancer and PAH." (PMID 36661515, 2023). "“PanCancer” panel (APC, FOXA1, RASSF1A) detected cancer with 72.4% sensitivity, 73.5% specificity and 72.8% accuracy.“CancerType” panel (SCGB3A1, SEPT9, and SOX17) discriminated TOO with 80.0%, 98.9%, and 85.1% specificity for breast, colorectal, and lung cancer, respectively." (PMID 36980276, 2023). "Two of the most frequently dysregulated transcription factors are co-expressed in lung cancer and PAH (FOXM1 and FOXF1), while the other six frequently deregulated transcription factors are co-expressed only in lung cancer (TCF21, SOX17, TAL1, LMO2, KLF2, and TBX4)." (PMID 36661515, 2023). "SOX17 (SRY-box containing gene 17) is a member of the SRY-related high mobility group (HMG) box family of TFs, related to embryogenesis and the negative modulation of the WNT/β-catenin and TCF signaling pathway in lung cancer." (PMID 36101460, 2022). "This confirmed the utility of CDO1, TAC1, HOXA7, and SOX17, while newly tested genes were not as effective for lung cancer detection." (PMID 32138766, 2020). "Four genes (HOXA9, RASSF1A, SOX17, and TAC1) were identified as the best biomarkers (all p < 0.001) and incorporated into a logistic classifier: Probability of lung cancer = ex/(1 + ex), where x = 1.69 + 1.48 × log (HOXA9) − 1.25 × log (RASSF1A) + 0.27 × log (SOX17) + 0.16 × log (TAC1)." (PMID 29796119, 2018). "Therefore, we advocate that methylated SOX17, CDO1, ZFP42, TAC1, FAM19A4, FHIT, MGMT, p16, and RASSF1A are useful in the screening and auxiliary detection of lung cancer." (PMID 28644424, 2017). "Hypermethylation and/or the downregulation of some of the genes identified in our study (e.g. ALDH1A2, HOXA5, MT1E, SOX17) have been reported in other cancers, but not yet in lung cancer." (PMID 22768131, 2012). "Moreover, FOXF1 is also co-expressed in the CCP of the LC RNA-Seq datasets, along with seven of the most frequently dysregulated TFs (FOXM1, SOX17, TAL1, TCF21, TBX4, LMO2, and KLF2), suggesting its importance as a regulator of gene expression during lung cancer progression." (PMID 36661515, 2023). "Recent studies have reported SOX17 methylation in lung cancer, but not at the stage level." (PMID 24369052, 2013).
breast carcinoma (28 papers, 2010 to 2025). "Chimonidou and colleagues demonstrated in three studies that methylation status of three tumor-associated genes (CST6, BRMS1, and SOX17) can be detected in circulating tumor cells of breast cancer patients." (PMID 29190932, 2017). "Our present data indicate a direct association between SOX17 promoter methylation in CTCs and ctDNA in patients with breast cancer." (PMID 29069768, 2017). "The methylation of SOX17 has also been linked with poor survival of breast cancer." (PMID 33833773, 2021). "SOX17 is downregulated by promoter hypermethylation, contributing to the activation of the Wnt signaling pathway in breast cancer establishment and progression." (PMID 36101460, 2022). "According to research, the SOX17 tumor suppressor gene was shown to be hypermethylated in CTCs from breast cancer patients." (PMID 35982906, 2022). "SOX17 is downregulated in lung and breast cancer, is the first winning TF of these two types of cancer, and is, therefore, a potential general tumor suppressor biomarker related to ectoderm origin." (PMID 36101460, 2022). "SOX17 promoter methylation was detected in plasma ctDNA in patients with operable breast cancer, after surgical removal of the primary tumor." (PMID 33942482, 2021). "A high expression level of SOX17 would lead to decreased growth of breast cancer cell so as to improve the treatment of breast cancer patients." (PMID 31874629, 2019). "We have shown already in a limited number of patients that SOX17 promoter is highly methylated in CTCs isolated from patients with breast cancer, and in corresponding ctDNA samples." (PMID 29069768, 2017). "In early breast cancer, SOX17 methylation status in the EpCAM-positive CTC-fraction was found to be correlated with CK-19 mRNA expression (P = 0.006)." (PMID 29069768, 2017). "SOX17 was detected in 26/42 (61.9%) patients diagnosed with early breast cancer and in 21/33 (63.6%) patients that developed metastasis." (PMID 29069768, 2017). "Promoter methylation of SOX17 was observed in 24/92 (26.1%) patients with early breast cancer, in 22/61 (36.1%) patients with metastatic disease and in 1/49 (2.0%) healthy individuals." (PMID 29069768, 2017). "In early breast cancer, SOX17 promoter methylation in the EpCAM-positive CTC-fraction was associated with CK-19 mRNA expression (P = 0.006) and worse overall survival (OS) (P = 0.044)." (PMID 29069768, 2017). "It is also interesting to note that in most early breast cancer patients that relapsed early, SOX17 gene promoter was found highly methylated in the primary tumour, in the EpCAM-positive CTC-fraction and in ctDNA." (PMID 29069768, 2017). "We identified networks regulated by known cancer drivers such as GATA3 and FOXA1 (breast cancer), SOX17 and FOXA2 (endometrial cancer), and NFE2L2, SOX2, and TP63 (squamous cell lung cancer)." (PMID 25994056, 2015). "For instance, methylated LINE1 and methylated SOX17 DNA accumulated in gastric juice-derived exosomes, and lincRNA-p21 was detected in extracellular vesicles from cervical carcinoma cells and breast cancer cells." (PMID 26582468, 2015). "In breast cancer cells, SOX17 is distinctly upregulated in CSC-like (SP) cells in conjunction with the activation of Wnt/β-catenin signaling pathway." (PMID 24885671, 2014). "Moreover, SOX17 low expression has been shown to associate with cisplatin or radiation resistance in colorectal cancer, endometrial cancer, or rat mammary carcinoma, suggesting the pivotal role(s) of SOX17 down-regulation in therapy-resistant cancers." (PMID 30777052, 2019). "In conclusion our findings indicate a direct association only between SOX17 promoter methylation in CTCs and ctDNA both in patients with early breast cancer and in patients with metastatic disease but not for the other genes studied." (PMID 29069768, 2017). "SOX17 methylation status in CTCs and ctDNA was comparable and was associated with CK-19 expression but was not reflecting the status of primary tumours in breast cancer." (PMID 29069768, 2017).